OR52A5 (olfactory receptor family 52 subfamily A member 5)
Description:
Odorant receptor.
Synonyms: OR11-33
Tractability: Antibody: UniProt places it where antibodies can reach, with medium confidence; UniProt predicts a signal peptide or a membrane-spanning region; its Gene Ontology location is reachable by antibodies, with medium confidence.
Gene: Protein-coding gene on chromosome 11 (5,128,776 to 5,138,356, reverse strand). Ensembl gene ENSG00000171944.
Subcellular location: Cell membrane
Pathways (Reactome):
Sensory Perception: Expression and translocation of olfactory receptors
Gene Ontology:
Molecular function: olfactory receptor activity; G protein-coupled receptor activity
Biological process: sensory perception of smell; detection of chemical stimulus involved in sensory perception of smell; G protein-coupled receptor signaling pathway; nervous system process
Cellular component: membrane; plasma membrane
Genetic constraint (gnomAD): Loss-of-function variants: 16 observed, 19.11 expected, observed/expected ratio (o/e) 0.84, 90% interval 0.57 to 1.27. The upper end of that interval is the gene's LOEUF score, 1.27, which puts it in group 5 of 6, group 1 being the genes least tolerant of losing a copy. Missense variants: 410 observed, 398.51 expected, observed/expected ratio (o/e) 1.03, 90% interval 0.95 to 1.12. Synonymous variants: 136 observed, 141.65 expected, observed/expected ratio (o/e) 0.96, 90% interval 0.83 to 1.11.
Homologues: Orthologues: chimpanzee OR52A5 (98% identical), macaque OR52A5 (97% identical), rabbit OLFR68 (82% identical), mouse Or52a5 (81% identical), mouse Or52a5b (81% identical). Paralogues in human: OR52A1 (73% identical), OR52E2 (51% identical), OR52N4 (51% identical), OR52N5 (50% identical), OR52M1 (50% identical), OR52E4 (49% identical), OR52E8 (49% identical), OR52J3 (49% identical), OR52N2 (49% identical), OR52N1 (49% identical), OR52R1 (49% identical), OR52D1 (49% identical), and 39 more.